STAT3 (signal transducer and activator of transcription 3)
Diseases named in the same sentence as STAT3 in open-access papers (continued):
Sharing a sentence is not in itself a finding about the gene and the disease.
tumor (continued). "Furthermore, whether PDLIM2 is involved in therapeutic resistance and whether PDLIM2 exerts its tumor suppressor role through targeting RelA and/or STAT3 have not been examined in any cancer type." (PMID 31757943, 2019). "Interestingly, cancer cells were more susceptible to concurrent modulation of any two of the EGFR, Src, and STAT3 proteins but not to the inhibition of the single proteins alone, thus suggesting the need for multiple-targeted therapy approaches for this deadly neoplasia." (PMID 29914167, 2018). "In addition, STAT3 signaling has been found to regulate both innate and adaptive immunity by increasing the expressions of growth factors and cytokines including TGF-β, VEGF, interleukin 6 (IL-6), and IL-10, which collectively repress the host immune response and facilitate tumor immune evasion." (PMID 30046565, 2018). "Overall, we observed that OP-D could significantly inhibit tumor growth without any apparent side effects as well as substantially reduce expression of p-STAT3 and augment the expression of various pro-apoptotic markers, thereby exhibiting significant anti-proliferative and pro-apoptotic potential." (PMID 30413072, 2018). "Interestingly, both STAT3 and MALAT1 over-expression occurred commonly in the tumor, and presumably such a co-occurrence might lead to tumor malignant transformation, it is likely that MALAT1 might act as a downstream effector of STAT3 in accelerating tumor progression." (PMID 30591689, 2018). "Importantly, identifying an agent that could inhibit STAT3 activity driven through an EGF, IL-6 and IL-11 ligand/receptor system may limit compensatory or re-activation of STAT3 and potentially reduce the likelihood of tumor resistance." (PMID 30572654, 2018). "In addition to activating the JAK/STAT3 pathway via phosphorylation of STAT3, the IL-6/IL-6R interaction leads to low E-cadherin expression and high vimentin expression as well as upregulated expression of Snail, ZEB1, ZEB2, Twist and other transcription factors that promote tumor metastasis." (PMID 30157906, 2018). "Interestingly, compared to tumor-free peripheral (TFB) brain and normal human astrocytes (NHA), FDPS protein expression and enzyme activity were detected at high degree in tumor mass where a correlation with canonical oncogenic signaling pathways such as STAT3, ERK and AKT was also documented." (PMID 29075041, 2017). "Considering that STAT3 was not commonly activated in normal epithelial cells, it would be interesting to investigate whether the inhibition of STAT3 signaling could decrease tumor progression in mouse ASCC." (PMID 28747781, 2017). "However, STAT3 is dispensable for subsequent tumour growth, irrespective of CD8 status." (PMID 28276425, 2017). "Moreover, the processing of NF-κB2 p100 to NF-κB2 p52 and the expression of c-Myc, STAT3 and p-STAT3 decreased in the RANK-N group compared with the control group, suggesting that RANK-N might inhibit tumor progression by suppressing alternative NF-κB and STAT3 signaling." (PMID 29202831, 2017). "To further examine whether activation of STAT3 is essential for ESCC cells to grow and form tumor, we established patients-derived xenografts in SCID mice from primary tumors EG30 and EG37, which contained high level pSTAT3, and EG2 and EG14 that expressed low level of phosphorylated STAT3." (PMID 29179470, 2017). "Indeed, our unpublished data suggest that STAT3 may be more important for tumor cell-microenvironment interactions rather than for direct cell survival." (PMID 28750090, 2017). "Small interfering RNA-mediated targeting of SOCS3 resulted in increased STAT3 phosphorylation and NK-mediated killing of tumor targets, which suggests that SOCS3 may be a negative regulator of NK activity and therapeutic targeting of SOCS3 in NK cells may potentiate killing of tumor targets." (PMID 27148255, 2016).
tumor (continued). "Although several mechanisms, such as PI3K and STAT3 signaling pathways via PTEN inhibition, of PD-L1 regulation on tumor cells have been reported, the cellular interactions between tumor cells and tumor stromal cells responsible for PD-L1 expression have remained unknown." (PMID 25889536, 2015). "Dependent on the patient-specific background, differences in STAT1 and STAT3 levels, their specific activation mechanism as well as the extent of their phosphorylation may be decisive for generating either a tumour-promoting or a tumour-suppressive effect (or none of the two)." (PMID 25880691, 2015). "However, the tanshinone- 1-driven reduction of hypoxia-induced HIF-1α accumulation could not be correlated with its effect on Stat3 in either endothelial or tumor cells." (PMID 26202747, 2015). "Taken together, these results suggest that therapeutic efficacy of dendritic cell-mediated vaccination approaches rely not only on effective antigen presentation, but also on highly effective anti-tumor T cell-mediated responses, which may not be influenced by STAT3 signaling." (PMID 24806510, 2014). "Since the factors have different and potentially complementary effects on tumor cell activities, including apoptosis, proliferation and migration, further investigation into whether and how PKR is involved in the crosstalk between NF-κB and STAT3 may be required." (PMID 25360179, 2014). "Importantly, STAT3 signaling is not confined to regulating tumor cell intrinsic pathways that control the microenvironment; it is also a key player in the development of “reactive” or inflammatory stromal cells that have been shown to promote PCa tumor aggressiveness." (PMID 24722453, 2014). "Finally, in “positive” tumors, a majority of nuclei showed staining, suggesting that the presence of activated STAT3 or STAT5 in a given cancer specimen was an intrinsic property of that tumor, and did not merely reflect the properties of a minor sub-population." (PMID 24762632, 2014). "Similarly to what observed in TPC-1 and the other RET-activated cell lines in vitro, JAK inhibitor led to a significant decrease of phospho-S6 and phospho-STAT3 levels (p<0.001) in the tumor, while no decrease was observed in vehicle or AZD6244- treated tumors." (PMID 23056499, 2012). "Whether inhibition of STAT3 in OS-1 tumor cells directly inhibits proliferation is not known." (PMID 22530037, 2012). "We have shown LLL12 to be an effective inhibitor of STAT3 and it has been shown to reduce to reduce tumor size in vivo but it remains to be seen whether or not LLL12, in conjunction with available BBBD methods, can effectively cross the barrier and suppress tumor growth." (PMID 21526200, 2011). "Notably, p-STAT3(Tyr705) was detected in a very minor component of the tumoral nuclei in the initial biopsy and was variably expressed in the post-anti- IGF1R treatment biopsy, ranging up to approximately one-half of the tumor cells in one microanatomical region." (PMID 21494688, 2011). "However, the therapeutic application of the complex did not suppress metastasis because the complex could not reverse tumor cell-induced STAT3 activation and neither activate IFNγ/STAT1 signaling and autophagy." (PMID 21931823, 2011). "Although the precise mechanism is required further investigation, tumor cell-induced STAT3 activation may largely be responsible for the suppression of IFNγ/STAT1 signaling and Th1 responses in mice treated with the TLR4/9 agonist complex after tumor cell inoculation." (PMID 21931823, 2011). "Thus, although rapid dephosphorylation of Stat3 by three PTPs may initially serve to protect skin from UVB-mediated carcinogenesis, this mechanism is overcome by other effects induced by UVB that ultimately lead to activation of Stat3 and tumor development." (PMID 20421975, 2010).
tumor (continued). "Importantly, normal SVZ cells responded in a different way; indeed, by chemically stabilizing HIF-1α, REDD1 was transiently upregulated and Akt/mTOR pathway was not inhibited, unlike in tumor cells, following exposure to high oxygen tension, and Akt and Stat3 were eventually upregulated by CoCl2." (PMID 19587783, 2009). "In vivo, STAT3 knockdown suppressed tumor formation and hepatosplenomegaly in mice inoculated with Ba/F3 cells expressing NPM-ALK, and these phenotypes were rescued by wild-type STAT3, but not by the T714A mutant." (PMID 41882193, 2026). "In lapatinib resistance models, chronic drug exposure induces p-STAT3 nuclear translocation in HGC-27 cells, upregulating NONHSAT160169.1, which enhances tumor stem cell properties and resistance via the hsa-let-7c-3p/SOX2 axis." (PMID 41550841, 2026). "This consistent downregulation, coupled with negative correlations to STAT3 and VCAM1 expression, especially in LSCC, supports the notion of SOX30 as a tumor suppressor." (PMID 41373817, 2025). "It is important to clarify that not all of these proteins act exclusively as tumor suppressors; some, such as EGFR, STAT3, SRC, and HSP90AA1, are oncogenic drivers whose inhibition can suppress cancer growth." (PMID 41150809, 2025). "In prostate cancer lacking PTEN, activated JAK2/STAT3 signaling established an immunosuppressive tumor microenvironment via SASP factors such as CXCL1, CXCL2, and IL-6 and resulted in tumor growth and chemoresistance." (PMID 40862837, 2025). "Evaluation of gene expression can provide insightful information about the tumor microenvironment.Until now, to our knowledge, the JAK2/STAT3/CTLA4 axis has not been investigated for tissue-specific gene expression at the mRNA levels in OSCC." (PMID 40092547, 2025). "In the mouse model, luteolin effectively inhibited tumor growth and downregulated the expression of phosphorylated JAK2 and STAT3 without altering the total protein levels of JAK2 and STAT3." (PMID 40051568, 2025). "Despite the importance of the GSK3β/STAT3 axis in this process, we observed that inhibition of GSK3β or STAT3 signaling does not generate valuable survival benefits in GBM tumor–bearing mice." (PMID 40131864, 2025). "Tumor-infiltrating lymphocyte (TIL) cultured from IDH-wildtype tumors demonstrated limited expansion following anti-PD-1, a CSF1R inhibitor, or a STAT3 inhibitor treatment, without clear cluster-specific differences." (PMID 40643554, 2025). "In triple-negative breast cancer models, OC’s dual inhibition of IL-6/STAT3 and COX-2/mPGES-1 pathways reduced Th17/Treg cross-talk by 40%, diminishing IL-17A-driven PD-L1 expression on tumor cells while augmenting CD8+ T cell cytotoxicity." (PMID 40564985, 2025). "For example, STAT3 inhibitor Napabucasin (also known as BBI608), which inhibits the immunosuppressive potential of MDSCs without limiting anti-tumor T-cell responses." (PMID 39990210, 2025). "Research suggests that PI3Kβ, rather than PI3Kα, is a key driver of STAT3 activation in the absence of PTEN, facilitating tumor immune evasion and ultimately leading to drug resistance." (PMID 40303296, 2025). "Results of this part of experiments showed that in tumors originating from U87MG cells with deleted STAT3 the parent TMZ accumulates to the high extent, but it is not seemingly converted to its active metabolite resulting in an uninhibited growth of tumor." (PMID 38654280, 2024). "CD24 alters Signal Transducer And Activator Of Transcription 3 (STAT3) expression via SRC Proto-Oncogene, Non-Receptor Tyrosine Kinase (Src), which leads to tumor invasion and metastasis." (PMID 38360723, 2024). "We found that phosphorylated STAT3 and ARF6 were significantly upregulated in tumor tissues compared with corresponding adjacent non-tumor tissues." (PMID 37716993, 2023). "Although the mechanism of STAT3 suppression by SHP-1 as a tumor suppressor mechanism is well-established, the SHP-1-mediated tumor-friendly molecular mechanism is not." (PMID 38203502, 2023).
tumor (continued). "A dose of 0.625 × 106 STAT3–/– T cells significantly prolonged survival, but did not eliminate ALL tumor cells." (PMID 37526084, 2023). "The results showed that 1 h after administration, the phosphorylation of ERK, STAT3 and STAT5 in tumor tissues in each group was not significantly inhibited, possibly due to the short administration time, the inhibition effect was not obvious." (PMID 37036582, 2023). "In pancreatic cancer, inhibiting STAT3 along with gemcitabine effectively increased MVD and facilitated the delivery of gemcitabine to tumours without changes in the stromal collagen or hyaluronan levels." (PMID 38067120, 2023). "It seems possible that hypoxia-related mechanisms also influenced the tumor development in our study, although we did not observe a direct regulation of HIF by STAT3 in COL1+ fibroblasts in an oxygen-independent manner." (PMID 35326623, 2022). "Accordingly, the activation of Stat3 and expression of Vegfa, Vegfb, and Vegfc in GK1 tumours between Rag1–/‐ and Rag1–/‐ Pdia4–/– mice were not altered." (PMID 35170261, 2022). "The average number of tumor colonies formed was not significantly different between DMSO control treatment of vector control cells and the cells with constitutively activated STAT3, 214, and 209, respectively." (PMID 34482626, 2022). "In human glioma patients and in a rat orthotopic tumor model a negative correlation between CK2 and STAT3 phosphorylated at Ser727 has been demonstrated." (PMID 36009534, 2022). "Incubating tumor cells in osteoclastic CM led to a noticeable rise of JAK1 and STAT3 phosphorylation in IL20RB-overexpressing A549 cells, but not in control A549 cells." (PMID 36006737, 2022). "Inhibition of STAT3 and EGR1, but not MAPK3 and EGR2, significantly abrogated the capacity of tumor cells to form cell-in-cell structures upon incubation with IFNγ-stimulated T cells and with T cell secreted granules." (PMID 36124553, 2022). "Our results showed that Stattic selectively inactivated STAT3 by inhibiting STAT3Y705 phosphorylation in PANC-1 cells, but not in BxPc-3 cells, suggesting the difference in anti-tumor mechanism of Stattic in different PCCs." (PMID 35288541, 2022). "Although we detected the other typical tumor signaling pathways including MAPK, JAK/STAT3, and Wnt/β-catenin signaling pathways, it had no differential expression between Lv-GPM6A and the empty vector." (PMID 36405247, 2022). "Interestingly, a seminal transcriptomic study in HCC patients identified a unique association between NF-kB and STAT3 activation in the adjacent non-tumor tissue, but not the tumor counterparts, and HCC recurrence, emphasizing the pivotal role of these pathways in tumor progression and relapse." (PMID 35267563, 2022). "Its primary pro-tumor mechanism is the activation of canonical signaling pathways mediated by the ObR-b receptor, such as JAK2/STAT3, PI3K/AKT and MAPK/ERK, and by non-canonical pathways such as PKC, JNK, MAPK/p38 and AMPK." (PMID 36291097, 2022). "p-STAT3 expression was consistently observed among immune dyad interactions, regardless of TME location or tumor type." (PMID 35316217, 2022). "However, STAT3 expression is not related to gender (OR = 0.88, 95% CI (0.54, 1.44), p = 0.609), age (OR = 0.54, 95% CI (0.21, 1.36), p = 0.191), capsular invasion (OR = 2.98, 95% CI (0.23, 38.29), p = 0.403), or tumor multiplicity (OR = 0.25, 95% CI (0.003, 19.28), p = 0.533)." (PMID 35463085, 2022). "Mostly, autocrine or paracrine IL-6 regulated tumor progression and promoted the conversion of non-stem cancer cells into cancer stem-like cells through JAK/STAT3 signaling pathway." (PMID 34657635, 2021). "Irrespective of these parameters, it has been observed that STAT3 activation in DCs and Tregs in TME involves the suppression of the anti-tumor immune responses." (PMID 34485117, 2021). "The expression of UBE2D3,p-STAT3, HK-2 and PFKL was reduced in the tumor of the shUBE23D group whereas that of STAT3 exhibited no significant alternation." (PMID 34195079, 2021).
tumor (continued). "STAT3 is not just an important factor for PDAC migration but is also involved in many other hallmarks of cancer to promote tumor progression." (PMID 34178628, 2021). "No wonder an increased STAT-3 is detected in a vast majority of clinical HCC samples and is often positively correlated with tumor aggressiveness." (PMID 35127527, 2021). "The increase in RORyt and STAT3, both Th17 mediators, and in STAT5, a Treg-related mediator, was observed only in patients with COPD III and IV, who did not present neoplastic disease." (PMID 34206428, 2021). "In accordance with this finding, in this study, osimertinib failed to suppress p-STAT3 in H1975 cells, and we demonstrated that combined treatment with osimertinib and YHO-1701 induced synergistic tumor growth inhibition." (PMID 33758275, 2021). "CRISPR-Cas9 mediated knockdown of the transcription factor STAT3 (signal transducer and activator of transcription 3) gene in GBM cells has no significant impact on cell proliferation in vitro; however, it has marked effect on inhibiting tumor growth in vivo." (PMID 34571991, 2021). "In the orthotopic mouse model, we also confirm that overexpression of IL11 restores the levels of tumor metastasis and expression of phospho-STAT3 expression in the absence of MAFF, supporting a critical role of IL11 in MAFF-mediated tumor metastasis." (PMID 34262028, 2021). "Due to its role in controlling the activation of the STAT3 oncogene, SOCS3 is typically considered a tumor suppressor protein, although this is not always the case in immune cancers." (PMID 34604264, 2021). "Similar to CAF, TAM derived IL-6 amplifies undirected, that is, not tumor-targeted, inflammatory responses and promotes HCC via enhanced STAT3 signaling." (PMID 32899119, 2020). "In our experiments, the supplementation of TNuF inhibited EGFR, the downstream signaling protein STAT3, and the mitosis marker Ki-67, and upregulated the inhibitor PTEN, but did not influence chaperon protein HSP90 in LLC tumor cells." (PMID 32872195, 2020). "STAT3 inhibitors induced cell cycle arrest and reduced growth; it is not known how interleukin-8 influences the MPM tumor microenvironment in vivo, but interleukin-8 has the potential to retain antigen-presenting dendritic cells in the tumor." (PMID 33374980, 2020). "By contrast, STAT3 did not affect expression of CD86, CD80, or MHC II on vaccine-derived CD103+ cDC1s within tumor-draining lymph nodes (TdLNs)." (PMID 31947933, 2020). "Inhibition of STAT3 activation in neoplastic and TME cells is expected to elicit anti-tumor responses and reduce tumor resistance without being cytotoxic to non-malignant cells." (PMID 31698775, 2019). "Specific deletion of Stat3 from granule cell precursors in a spontaneous mouse model of SHH medulloblastoma completely protects male, but not female mice from tumor initiation." (PMID 31683879, 2019). "In nude mice, which are immunodepressed, tumour cell grafting did not induce an overt inflammatory response; therefore, the observed effect was due to inhibition of the GP130/JAK/STAT3 pathway in cancer cells and not in inflammatory cells." (PMID 31091767, 2019). "In tumor cell supernatants, tumor soluble factors induce activation of ERK, which results in MDSCs expansion, while TDEs trigger STAT3 activation without promoting MDSCs expansion." (PMID 31480382, 2019). "siRNA knockdown of STAT1 but not STAT3 reduced IFN-g- and IL-27-induced PD-L1 protein expression on tumor cells." (PMID 31730010, 2019). "In vivo inhibition of STAT3 activation by a negative mutant of STAT3 can significantly inhibit VEGF expression and angiogenesis, thereby limiting tumor growth and metastasis." (PMID 31885639, 2019). "Compared to GPRC5A wild-type cells, GPRC5A knockout cells have higher levels of activated-STAT3 and STAT3-regulated anti-apoptotic genes, independent of the presence of exogenous epidermal growth factor (EGF), resulting in enhancement of tumor progression." (PMID 30417009, 2018).